ACAP3 (ArfGAP with coiled-coil, ankyrin repeat and PH domains 3)
Description:
GTPase-activating protein for the ADP ribosylation factor family.
Synonyms: CENTB5; KIAA1716
Tractability: PROTAC: ubiquitination databases record sites on it; its protein half-life has been measured.
Gene: Protein-coding gene on chromosome 1 (1,292,376 to 1,309,609, reverse strand). Ensembl gene ENSG00000131584.
Subcellular location (Human Protein Atlas): Nucleoplasm; Golgi apparatus
Gene Ontology:
Molecular function: protein binding; GTPase activator activity
Biological process: actin cytoskeleton organization; neuron migration; regulation of neuron projection development
Cellular component: endosome membrane; cytoplasm
Genetic constraint (gnomAD): Loss-of-function variants: 57 observed, 87.15 expected, observed/expected ratio (o/e) 0.65, 90% interval 0.53 to 0.82. The synonymous counts are far from expectation, so gnomAD's model fits this gene poorly and the ratio says little. Missense variants: 1,208 observed, 1,036.5 expected, observed/expected ratio (o/e) 1.17, 90% interval 1.11 to 1.22. Synonymous variants: 628 observed, 444.14 expected, observed/expected ratio (o/e) 1.41, 90% interval 1.32 to 1.51.
Homologues: Orthologues: chimpanzee ACAP3 (99% identical), macaque ACAP3 (97% identical), mouse Acap3 (94% identical), dog ACAP3 (94% identical), rat Acap3 (93% identical), guinea pig ACAP3 (93% identical), pig ACAP3 (87% identical), tropical clawed frog acap3 (77% identical), zebrafish acap3b (73% identical), zebrafish acap3a (51% identical). Paralogues in human: ACAP2 (57% identical), ACAP1 (47% identical), ASAP1 (24% identical), ASAP2 (23% identical), ASAP3 (23% identical), AGAP1 (20% identical), AGAP3 (20% identical), ARAP1 (18% identical), ARAP2 (18% identical), AGAP2 (17% identical), AGAP5 (15% identical), AGAP6 (15% identical), and 16 more.
Diseases named in the same sentence as ACAP3 in open-access papers:
ACAP3 is named in the same sentence as 9 diseases in open-access papers, as found by Europe PMC text mining. Sharing a sentence is not in itself a finding about the gene and the disease. The quoted sentences say what the papers report.
liver cancer (3 papers, 2019 to 2023). An epithelial or non-epithelial malignant neoplasm that arises from the liver. "Another study found extremely down-regulated ACAP3 in patients with late-stage liver cancer compared to the early-stage." (PMID 37177979, 2023). "There is relatively little oncological literature on Acap3, however it has been identified as highly down-regulated in late-stage liver cancer patients." (PMID 34315405, 2021). "Further checking their mRNA level in different pathological stages showed that CD147, ARNO, and Rac1 expressions were markedly up-regulated, while ACAP3 expression was significantly down-regulated at stage IV of liver cancer." (PMID 31752956, 2019). "GEPIA bioinformatics analysis showed that CD147, Rac1 and an Arf6-specific GEF ARNO exhibited higher transcription levels in liver cancer tissues than in matched normal liver tissues, whereas, the mRNA level of Arf6 and other Arf6-specific GEFs or GAPs (except ACAP3) tended to be no different." (PMID 31752956, 2019).
epilepsy (1 paper, 2020). A brain disorder characterized by episodes of abnormally increased neuronal discharge resulting in transient episodes of sensory or motor neurological dysfunction, or psychic dysfunction. "In this connection, the present study aimed to carry out an analysis of associations of the possible participation of the ACAP3 gene intra-intronic minisatellite length polymorphism and its methylation status in neurological diseases, in particular epilepsy." (PMID 33276684, 2020). "Therefore, it is possible that ACAP3 as a GTPase-activating protein can react to both neurotransmitters and sex hormones, and the abnormalities in ACAP3 expression, in turn, can cause the development of sex-dependent clinical characteristics of epilepsy." (PMID 33276684, 2020). "All these statements concerning the molecular mechanisms of action of UPS29 and ACAP3 in the etiopathogenesis of epilepsy require further research." (PMID 33276684, 2020). "We suppose that genetic and epigenetic alterations UPS29 can modify ACAP3 expression and thereby affect the development and clinical course of epilepsy." (PMID 33276684, 2020). "This study aimed to carry out an association analysis of the length polymorphism and DNA methylation of the UPS29 minisatellite of the ACAP3 gene in patients with epilepsy." (PMID 33276684, 2020).
epileptic seizures (1 paper, 2020). "This fact may explain the identified associations of UPS29 with the clinical characteristics of epileptic seizures (type, duration, and frequency), assuming that this tandem repeat is involved in the modulating of ACAP3 expression." (PMID 33276684, 2020).
thyroid papillary carcinoma (1 paper, 2023). "A previous study suggested that downregulated ACAP3 was associated with ferroptosis, a type of cell death, in thyroid papillary carcinoma and implied a novel direction for cancer therapy." (PMID 37177979, 2023).
neurological diseases (1 paper, 2020). "Thus, taking into account the structural and functional features of proteins of the Arf GAPs family, as well as their possible combined effects with other factors and/or comorbidities, ACAP3 dysfunction can be associated with human pathologies, in particular with neurological diseases." (PMID 33276684, 2020).
ACAP3 also shares sentences with these, for which no sentence is quoted: cancer (1 paper); lung adenocarcinoma (1); Parkinson disease (1); tumor (1).